GLULP6 (glutamate-ammonia ligase pseudogene 6)
Gene: Processed pseudogene on chromosome 2 (194,129,354 to 194,130,266, reverse strand). Ensembl gene ENSG00000215043.
Diseases named in the same sentence as GLULP6 in open-access papers:
GLULP6 is named in the same sentence as 1 disease in open-access papers, as found by Europe PMC text mining. Sharing a sentence is not in itself a finding about the gene and the disease. The quoted sentences say what the papers report.
infectious disease (1 paper, 2023). A disorder directly resulting from the presence and activity of a microbial, viral, or parasitic agent in humans. "The DNAJC17P1/GLULP6 gene, which is located in the intergenic region, is known to be associated with susceptibility to infectious disease as well as educational attainment." (PMID 36768488, 2023).